ENSG00000264452
Synonyms: LOC124905068
Gene: Small nucleolar RNA gene on chromosome 21 (44,439,035 to 44,439,110, forward strand). Ensembl gene ENSG00000264452.
Gene Ontology:
Biological process: RNA processing
Cellular component: nucleolus
Homologues: Orthologues: mouse Gm22394 (63% identical), rat LOC120099065 (63% identical).